SFRP1 (secreted frizzled related protein 1)
Diseases named in the same sentence as SFRP1 in open-access papers (continued):
Sharing a sentence is not in itself a finding about the gene and the disease.
tumor (continued). "In line with our preceding results, the stable SFRP1 expression in HuH-6, HepT1 and HepG2 cells resulted in significantly impaired tumor cell growth and a strong decrease in colony formation and migration capacity compared to control cells." (PMID 32189106, 2020). "The SFRP1 epigenetic seems to be a crucial player in early breast tumorigenesis and needs to be explored to better understand the mechanisms of tumor development." (PMID 31947616, 2020). "On the contrary, among the known WNT antagonists, the secreted frizzled-related protein 1 (SFRP1) is often downregulated in various cancer entities, which indicates that SFRP1 has tumor-suppressive functions." (PMID 32189106, 2020). "While the role of SFRP1 as a tumor suppressor gene is well-established, some studies also reported the possible oncogenic properties of SFRP1 in cancers." (PMID 32074995, 2020). "In fact, SFRP1 suppressed tumor progression through epithelial-to-mesenchymal transition via the Wnt/β-catenin signaling pathway." (PMID 33282723, 2020). "Overexpression of SFRP1 in HB cell lines resulted in an inhibition of tumor cell growth, colony formation and migration and a decrease in WNT/β-catenin signaling activity." (PMID 32189106, 2020). "To study the functional relevance of SFRP1 gene silencing in HB, we assessed tumor cell characteristics after SFRP1 re-expression." (PMID 32189106, 2020). "OR-2003, but not OR-2100, displayed luciferase activity comparable to that of DAC and a stronger induction of endogenous tumor-suppressor genes, SFRP1 and UCHL1." (PMID 31370878, 2019). "In adjacent non-tumor tissues, the number of patients with SFRP1, SFRP2, and WIF1 methylation levels exceeding the cut-off value were 5 (2.7%), 7 (3.7%) and 41 (21.9%), respectively." (PMID 31830937, 2019). "Three genes, AXIN2, DKK3, and SFRP1, which are known as tumor suppressors in a broad range of human malignancies including NSCLC, are targeted by miR-582-3p and suppress their protein levels." (PMID 30621620, 2019). "Four genes (EPB41L2, HLA-DQB1, LTF and SFRP1) were consistently overexpressed across multiple PFS cutoff times in initial tumor samples of patients with disease progression following topotecan treatment." (PMID 31195594, 2019). "Usually, as tumor-suppressor gene, SFRP1 and SFRP2 methylation were inversely correlated with the mRNA expression, and the expressions were increased after demethylation treatment in CRC cell lines." (PMID 31830937, 2019). "Two tumor suppressor genes, sFRP1 and SMAD, were up-regulated by genistein as a consequence of direct regulation of miR-1260b." (PMID 31597327, 2019). "Consistently, previous studies showed that injection of sphere cells exposed to ex vivo recombinant SFRP1 protein in xenograft mice inhibits tumor incidence and growth." (PMID 30158579, 2018). "A recent comprehensive study on the context-specific roles of SFRPs analyzed promoter methylation, gene expression, and survival data from 8000 tumors of 29 cancer types, finding that only SFRP1 consistently functioned as a tumor suppressor." (PMID 30394013, 2018). "Accordingly, patients with Rab37 low, SFRP1 low and Oct4 high expression profile correlates with progressive tumor stages and poor prognosis." (PMID 30158579, 2018). "Strikingly, patients with expression profile of low Rab37/low SFRP1/high Oct4 (Rab37−/SFRP1−/Oct4+) in their tumor specimens showed the worst OS and PFS." (PMID 30158579, 2018). "Our results demonstrated that patients with concordantly decreased expression of both Rab37 and SFRP1 showed high expression of stemness marker Oct4 in their tumor specimens (P = 0.018)." (PMID 30158579, 2018). "Nevertheless, they also concluded that SFRP1 methylation was more frequent in patients with tumor grades III and IV, which is consistent to our finding." (PMID 30394013, 2018). "When we compared SFRP1 methylation status among tumor grades, a significant difference in methylation distribution was revealed (Pearson χ2 = 6.323; P = 0.042)." (PMID 30394013, 2018).
tumor (continued). "Together, these data indicated that SFRP1 secretion is crucial for Rab37-mediated cancer stemness suppression and treatment with rSRPP1 protein reduces tumor initiation ability." (PMID 30158579, 2018). "We further validated the essence of these studies with our pancancer analysis by showing that in 17 different cancers, SFRP1 expression is significantly downregulated in tumourous tissues compared to normal counterparts." (PMID 28218291, 2017). "In a previous study by our group, TGFβ signalling activation was considered to be the mechanism by which sFRP1 promotes the formation of tumours." (PMID 28169332, 2017). "Previous studies have reported increased SFRP1 methylation with age in both normal and tumor tissues." (PMID 28077379, 2017). "We determined that SFRP1, the prototypical family member, is downregulated during tumour formation, silenced by methylation and likely follows much of the dogma surrounding this gene family." (PMID 28218291, 2017). "Whereas, low expression of SFRP1, a tumor suppressor explains the rapid proliferation characteristics of these cells." (PMID 29187162, 2017). "When SFRP1 is re-expressed in tumor cells, invasion and cellular proliferation is suppressed suggesting that it is an important tumor suppressor protein." (PMID 28687085, 2017). "SFRP1 is a 35.4-kDa protein that has been proposed to be a tumor suppressor because of its role in antagonizing Wnt signaling." (PMID 28077379, 2017). "Three genes, including STK11, SFRP1 and CREB3L1, were involved in tumor-associated signaling pathway, and selected for further RT-PCR analysis." (PMID 27385214, 2016). "SFRP1 methylation was found to be related to tumor aggressiveness and, more importantly, negatively correlated with patients’ survival time." (PMID 26337424, 2016). "Accumulated evidences indicate that restoration of SFRP1 expression attenuates Wnt signaling and inhibits cell growth in certain tumor types." (PMID 27385214, 2016). "SFRP1 exerts its function in the Wnt signaling pathway as a well-known antagonist of the frizzled receptor, and has been suggested to be a tumor suppressor in several human cancers." (PMID 25719802, 2015). "Overall, our results demonstrate that miR-582-3p activates Wnt signalling by targeting AXIN2, DKK3 and SFRP1; enhances stem cell-like traits; and leads to tumour recurrence and poor prognosis in NSCLC patients." (PMID 26468775, 2015). "Taken together, these results confirmed that there was an inverse correlation between SFRP1 and β-catenin expression in PCa cell lines, which is consistent with the data obtained from tumor tissue samples." (PMID 25719802, 2015). "The evaluation of the methylation status of SFRP1 gene in clear cell RCC (ccRCC) from 10 patient-paired tissue samples using methylation-specific PCR (MSP) revealed hypermethylation in 8 of 10 tumor samples and 1 of 10 normal samples." (PMID 26198328, 2015). "SFRP1, a member of the sFRP family and a Wnt antagonist, is significantly downregulated and has tumour-suppressive effects in lung cancer." (PMID 26468775, 2015). "SFRP1 functions as a tumor suppressor and its expression is lost in many patient tumors because of promoter hypermethylation." (PMID 26170835, 2015). "For example, the MTUS1 and SFRP1 genes on chromosome 8p22 and 8p12-11.1 loci have been identified for their tumor suppression function in UBUC." (PMID 26307680, 2015). "AXIN2, DKK3 and SFRP1 have been identified as negative regulators of Wnt signalling and suggested to be tumour suppressors in a broad range of human malignancies including NSCLC14." (PMID 26468775, 2015). "Most interestingly, SFRP1 seems to be involved in BMP signaling cascade in both tumor models, i.e. independently of the mirrored subtype." (PMID 25036590, 2014). "Decreased epithelial SFRP1 protein expressions were found in crypts of most NAT samples which localized closely to the tumor." (PMID 25405986, 2014).
tumor (continued). "In combination with the statistically significant association of hypermethylation of SFRP1 with poorer patient survival, this suggests that the dysregulation of the WNT pathway is important for CCRCC tumor progression." (PMID 24454902, 2014). "Our in silico data clearly showed that in basal-like BT20 tumor cells SFRP1 is involved in modulating the canonical Wnt pathway." (PMID 25036590, 2014). "In the HumanMethylation450 BeadChip cohort, hypermethylation of SFRP1 was the only remaining statistically significant marker of poorer survival after tumor stage." (PMID 24454902, 2014). "As expected, quantitative RT-PCR demonstrates elevated expression of both Snail and Zeb2 in the pTD cells (2-fold) and tumours (>4-fold) relative to the CDβGeo cells along with suppression of Sfrp1." (PMID 23883065, 2013). "Four out of six neoplasias were found in the mice showing higher methylation at CGIs of all five genes Dkk1, Slc5a8, Hoxd1, Socs1 and Sfrp1 (B219, B220), of the four genes Dkk1, Hoxd1, Socs1 and Sfrp1 (B215), or of Dkk1 (B236)." (PMID 24204690, 2013). "Methylation of SFRP1, IRF8, APC and RASSF1A were significantly associated with increased tumor grade and stage in samples from Taiwan." (PMID 21599969, 2011). "Regarding the samples from Taiwan, methylation of SFRP1, IRF8, APC and RASSF1A were significantly associated with increased tumor grade, stage." (PMID 21599969, 2011). "This is indeed the case in some tumours, where restoration of sFRP1 expression inhibits both β-catenin/TCF activity and cancer cell growth." (PMID 19277043, 2009). "Two antagonists of WNT receptor signaling, WIF1 and SFRP1, were consistently downregulated both in the tumor epithelium and stroma." (PMID 19187537, 2009). "WNT stimulates tumor cell motility; conversely sFRP1-mediated WNT pathway blockade reduces motility." (PMID 19473496, 2009). "The in vivo results together with the data on in vitro proliferation suggest that higher levels of sFRP1 cause a stronger blockade of WNT pathway activity, leading to a more pronounced effect on the time to tumor onset and tumor outgrowth." (PMID 19473496, 2009). "In summary, these results suggest that sFRP1-mediated blockade of WNT pathway activity in tumor cells is an important factor contributing to the slower outgrowth of the MDA-MB-231/sFRP1 tumors in mammary glands." (PMID 19473496, 2009). "A pattern of tumor profiling emerged: complete hypermethylation of SFRP1, SEZ6L, LPPH1 and CXX1 was common in CRC and gastric cancers, but only partial or no methylation was seen in all other types of cancer studied." (PMID 19424480, 2008). "Both SFRP1 and SFRP5 methylation were shown to occur frequently and be tumour specific with a strong association to poor clinical patient outcome." (PMID 18826564, 2008). "Of these, SFRP1 is downregulated in both types of our tumor cells, and genes involved in calcium regulation pathway are not significantly changed." (PMID 17389037, 2007). "Among them, SFRP1 (secreted frizzled-related protein 1 gene), a putative tumor suppressor gene mapped onto chromosome 8p12-p11.1, a frequent loss of heterozygosity (LOH) region in human HCC, was found to be down-regulated in HCC." (PMID 17626620, 2007). "The fact that sFRP1 decreases p-ERK1/2 levels suggests that WNT-mediated ERBB transactivation has an important role in maintaining ERK1/2 signaling in these tumor cells." (PMID 17897439, 2007). "Of these, SFRP1 (secreted frizzled-related protein 1) was downregulated in tumor cells, and genes involved in calcium regulation pathway were not significantly changed." (PMID 17389037, 2007). "The frequent downregulation of sFRP1, and other Wnt antagonists, in colorectal carcinogenesis infers that tumour cells retain a requirement for Wnt signalling despite containing high levels of β-catenin and the reason for this is not clear at present." (PMID 16523202, 2006).
tumor (continued). "All six cases with SFRP1 hypermethylation were staged as pT2 and this rare change was therefore significantly related to tumour stage (P=0.02)." (PMID 15292941, 2004). "Notably, spatial single-cell transcriptomics identified SFRP1 as the most consistently reactivated tumor suppressor across eccDNA, bulk expression, and spatial datasets, based on predefined statistical and biological criteria, by Tazemetostat." (PMID 41744650, 2026). "SFRP1 acted as an oncogene and functioned as a tumour suppressor in a variety of tumours." (PMID 40418209, 2025). "Given its dual role in tumor suppression and adipogenesis, SFRP1 may not only directly influence Wnt signaling pathway activity in PAAD cells but also indirectly affect BA development or function." (PMID 41595468, 2025). "Likewise, sFRP1 can act as a tumour suppressor in epithelial cells but supports tumour growth via stromal expression." (PMID 41007281, 2025). "Indeed, while tumor cells exhibited increased quiescence in an SFRP1-OE PDA model, healthy cell transcriptomes remained unperturbed." (PMID 40770193, 2025). "Analysis of v-SVZ VMRs at their syntenic human coordinates (“Methods”) revealed significant enrichment of astrocyte-specific VMRs hypomethylation in SFRP1-OE tumor cells, confirming that SFRP1-OE rewires tumor cell methylomes along with their transcriptomes and morphology." (PMID 40770193, 2025). "Furthermore, Sfrp1 depletion in a mouse skin carcinogenesis model promoted early tumor initiation and tumorigenic potential." (PMID 40319033, 2025). "Specifically, SFRP1 downregulation may relieve its inhibitory effect on tumor cell proliferation while diminishing the inherent anti-tumor metabolic capacity of BA tissue, thus promoting PAAD progression." (PMID 41595468, 2025). "Therefore, further exploration of the specific mechanisms and functions of SFRP1/2 transcriptional expression and DNA methylation in regulating the tumor microenvironment is warranted." (PMID 39729237, 2025). "Patients with low SFRP1 expression showed larger tumor sizes and vascular invasion." (PMID 39729237, 2025). "While some studies suggest that SFRP1 is a tumor suppressor, recent research has shown that it may have oncogenic properties and could be a useful cancer biomarker." (PMID 40365190, 2025). "In addition, tumor retrieval 24 d after transplantation showed a drastic decrease in the percentage of CSCs in Sfrp1 KO mice." (PMID 38625488, 2024). "To examine whether Sfrp1 in the tumor environment affected tumor growth, we inoculated LLC cells into WT and Sfrp1−/− (Sfrp1 KO) mice and evaluated their growth." (PMID 38625488, 2024). "Sfrp1 in tumor tissues is expressed in a subset of vascular ECs." (PMID 38625488, 2024). "Although the detailed effects of Sfrp1 in tumor tissues remain unknown, we demonstrated that Sfrp1 contributes to tumor growth by regulating CSC proliferation." (PMID 38625488, 2024). "SFRP1 displayed a positive performance in tumor immune infiltration, especially in MCs." (PMID 39064602, 2024). "Therefore, immunostaining was performed to examine the effect of Sfrp1 on the structure of blood vessels in tumor tissues." (PMID 38625488, 2024). "Analysis of mice lacking Sfrp1 showed that tumor growth was suppressed in Sfrp1-deficient tumor tissues." (PMID 38625488, 2024). "Our data suggest that SFRP1 may be an important mediator that tempers Wnt signaling in the tumor microenvironment." (PMID 38554160, 2024). "The tumor suppressor gene SFRP1 is downregulated in tumor tissues." (PMID 39617900, 2024). "However, the cells that produce Sfrp1 in the tumor microenvironment and the function of Sfrp1 remain underexplored." (PMID 38625488, 2024). "While most studies have examined SFRP1 as an autocrine tumor suppressor, more recent data has suggested a more complex mechanism which could involve cross talk with the tumor microenvironment (TME)." (PMID 38554160, 2024). "Compared to the WT group, tumors in Sfrp1 KO mice showed reduced tumor growth (p < 0.01)." (PMID 38625488, 2024).
tumor (continued). "The mechanism of action of Sfrp1 in tumor tissues is not well understood." (PMID 38625488, 2024). "Numerous miRNAs have been proved to accelerate tumor progression by targeting SFRP1." (PMID 38309281, 2023). "Since SFRP1 is a negative regulator of Wnt-signalling, we wanted to learn whether a reduction in SFRP1 abundance in CMTs correlated with canonical Wnt-pathway activation in our canine tumours." (PMID 37402051, 2023). "We then co-stained for PKMYT1, TGF-α, SFRP1 and SFRP2 with the fibroblast markers: Collagen IVα1, PDGFR-α and α-SMA, which were respectively associated with ECM remodeling, immune modulation/M2 polarization and tumor proliferation/immune suppression." (PMID 37091166, 2023). "Notably, Akt/NICD1+ Sfrp1 (A/N+Sfrp1) mice developed a smaller tumour load 5 weeks after plasmid injection compared to Akt/NICD1/ Vector (A/N+V) mice." (PMID 38050190, 2023). "Importantly, SFRP1’s role as a tumour suppressor has been elucidated across a plethora of literature." (PMID 37345165, 2023). "This is supported by the observation of reduced SFRP1 expression in lower stage PDAC tumor tissue." (PMID 37333823, 2023). "Hence, SFRP1 expression is counter-intuitively often found in younger patients, with higher tumour stage, -size and -grade." (PMID 37402051, 2023). "Moreover, the level of SFRP1 was significantly higher in tumour samples obtained from patients with stage III NSCLC compared to tumour samples obtained from patients with stage II (644.83 vs. 204.38; p = 0.012)." (PMID 37999144, 2023). "SFRP1 is believed to be an anti‐tumor factor due to its low expression level in human cancers." (PMID 36259450, 2023). "We hypothesize that HPβCD quite likely can bind to SFRP1 and accentuate its tumour suppression characteristics." (PMID 37345165, 2023). "Here, we demonstrated DNMT3A-mediated SFRP1 methylation promoted tumor progression in NSCLC." (PMID 35860691, 2022). "For example, SFRP1, a tumor marker gene, showed elevated expression values in the black region." (PMID 36376296, 2022). "Furthermore, SFRP1 displayed a positive performance in tumor immune infiltration, especially in mast cells." (PMID 35892344, 2022). "SFRP1 mRNA was downregulated in all tumor subtypes in a similar manner to TCGA CIMP-RCC." (PMID 36455002, 2022). "This suggests that promoter hypermethylation of SFRP1 may be more relevant for tumor progression than for tumor genesis." (PMID 34830873, 2021). "Regarding the female dogs, we sequenced 79 BC-related genes, and those with high number of variants shared by tumor fragments and plasma were GATA3 and mTOR (missense), SFRP1 (frameshift insertion), BRCA2 (multi hit), FOXC2, ATM, TGFBR3, and BRIP1 (missense and multi hit mutations)." (PMID 34680380, 2021). "SFRP1 promoter hypermethylation may impact the speed with which cancer progresses or affect the tumor’s sensitivity to chemotherapy." (PMID 34830873, 2021). "However, another study showed that hsa_circ_0087378 (circNTRK2) was down-regulated in tumor tissues and cell lines in ER-positive BC, and hsa_circ_0087378/miR-1260b/SFRP1 was concluded as its possible regulatory mechanism." (PMID 32653032, 2020). "However, we also discovered that SFRP1 is thought to be a tumor suppressor that is epigenetically silenced by DNA methylation." (PMID 33193589, 2020). "In other words, SFRP1 is a tumor-suppressor in physiological conditions." (PMID 31947616, 2020). "Moreover, a treatment of the tumor cells with 5-aza solely restored SFRP1 expression in all four cell lines, indicating that DNA methylation is responsible for the SFRP1 suppression in HB cell lines." (PMID 32189106, 2020). "In addition, studies have indicated that use of Wnt-modulatory peptides, SFRP1, or SFRP1-derived peptides reduce HCT116 xenograft tumor development in nude mice." (PMID 33374459, 2020).